S100A9 (S100 calcium binding protein A9)
Diseases named in the same sentence as S100A9 in open-access papers (continued):
Sharing a sentence is not in itself a finding about the gene and the disease.
tumor (continued). "Further, tumours with elevated numbers of CD33+S100a9+ cells were generally higher-grade tumours and poorly differentiated with detectable satellite lesions." (PMID 32747748, 2020). "With a sizeable fraction of the examined samples showing clearly higher expression of S100A8 and S100A9 in the tumor vs. in the tumor stroma these tissue areas were statistically distinguishable." (PMID 32733643, 2020). "Our earlier data also revealed that inhibition of S100A9 represented a promising strategy for the treatment with neoplasm." (PMID 33203795, 2020). "S100a9 is an intratumoral immunosuppressive cell marker, which maintains tumor progression in the TME including the regulation of antitumor immune cells." (PMID 33260154, 2020). "Displaying expression levels in the tumor vs. in the healthy stroma revealed a clear accumulation of S100A8 and S100A9 in the tumor, similar to that observed in the MS images." (PMID 32733643, 2020). "We also demonstrated significant correlations with increased levels of these cytokines and CD33+S100a9+ cells in BTC tumours." (PMID 32747748, 2020). "It is universally acknowledged that S100A9 has both intracellular and extracellular functions in tumor microenvironment." (PMID 33203795, 2020). "Altogether, imaging S100A8 or S100A9 expression allowed to differentiate the tumor tissue from the healthy stroma, and to a lesser extent distinguished between the tumor and the tumor stroma or the healthy epithelium." (PMID 32733643, 2020). "Once secreted in the extracellular space, S100A9 acts as a chemo-attractant, recruiting further inflammatory cells and creating an inflammatory microenvironment that promotes tumor development." (PMID 33396529, 2020). "The network associated with regulation of tissue invasion by tumor cell lines and lipid export was connected by five proteins: ACAT1, CAV1, CTSS, S100A12, and S100A9." (PMID 33607292, 2020). "Screening for tumor-associated LMW protein and lipid changes in HNSCC tissue, here we identify S100A8, S100A9 and specific phospholipids to accumulate and lysophosphatidylcholine to be depleted in the tumor." (PMID 32733643, 2020). "Although displaying a heterogenous distribution within the examined ROIs, expression of either S100A8 or S100A9 clearly distinguished between healthy stroma and tumor areas, and proved to be a statistically reliable positive tumor marker of the specimen." (PMID 32733643, 2020). "Elevated S100A9 in tumor microenvironment released from cancer cells, inflammatory cells, or MDSCs fuels RAGE- dependent p38 MAPK signaling cascade and also the TLR4-dependent NF-κB signaling cascade." (PMID 33117687, 2020). "BTC-derived factors promote suppressive myeloid cell expansion, and higher numbers of CD33+S100a9+ cells in resectable BTC tumours correlates with more aggressive disease." (PMID 32747748, 2020). "It has been found that increased levels of S100A9 and MDSCs in tumor tissue and peripheral blood of CRC patients were related to neoplastic progression." (PMID 33117687, 2020). "Increased CD33+S100a9+ staining positively correlated with higher tumour grade, differentiation and the presence of satellite lesions." (PMID 32747748, 2020). "RT-PCR analysis showed that the mRNA levels of Bv8, S100a8, S100a9, and Mmp9 were significantly higher in the lungs of tumor-bearing mice after 2 weeks of sunitinib treatment than those in tumor-bearing control mice." (PMID 32993785, 2020). "S100A9 has been found to be strongly over-expressed in many tumors, leading to carcinogenesis, tumor development, and metastasis." (PMID 33203795, 2020). "The extracellular S100A9 protein also acts as a ligand and interacts with surface receptors on tumor cells, including the receptor for advanced glycation end product (RAGE), Toll-like receptor 4 (TLR4) and CD147." (PMID 33203795, 2020).
tumor (continued). "Reassuringly, several known CRC biomarkers, such as CEA, S100A9, and tenascin C, were among those overexpressed in the tumor tissues in our findings, validating our experimental approach." (PMID 32587829, 2020). "Selected regions of the neoplastic and healthy tissue areas were subjected to histopathological scoring for determining S100A8 and S100A9 expressions in the tumor, tumor and healthy stroma as well as in the healthy epithelium." (PMID 32733643, 2020). "The significant positive correlation between IL-6 and GM-CSF with infiltration of CD33+S100a9+ cells indicates that these cytokines contribute to progression by modulating the immune composition of the tumour." (PMID 32747748, 2020). "As recruited monocytes mature, they lose S100A8 and keep S100A9 expression and recruit more inflammatory cells, resulting in tumor cell proliferation and invasion." (PMID 33117687, 2020). "After a series of validation experiments for the concerned genes, it was found that IL6, GM‐CSF (CSF2), IL11, CCL3, S100A8 and S100A9 were significantly decreased in the gut tumours of ApcMin/+ TLR4−/− mice compared with ApcMin/+ WT mice." (PMID 31650683, 2020). "The calcium-binding pro-inflammatory proteins S100A8 and S100A9, which are ubiquitously present in the tumor microenvironment, drive the accumulation of MDSCs through increased recruitment to primary tumor and pre-metastatic niche." (PMID 32793192, 2020). "In summary, our findings reveal that G‐MDSCs enhance CRC cell stemness via exosomes and exosomal S100A9 in the tumor microenvironment, especially under hypoxic conditions." (PMID 31559140, 2019). "The area under the ROC curves of S100A9 for tumor and normal bone tissues was 0.827 [95% confidence interval (CI), 0.724–0.912] (P = 0.008)." (PMID 31055998, 2019). "S100A9 secreted from tumor cells is an important regulator of the tumor microenvironment and is an endogenous activator of TLR4." (PMID 31727865, 2019). "Our findings deepen the understanding of the molecular mechanisms involved in MDS reprogramming of MSCs and indicated the essential role of S100A9 in tumor-environment interactions in bone marrow." (PMID 31727865, 2019). "The exact mechanism of S100A8/S100A9 in PMN formation is unclear, although S100A8/S100A9 is crucial for intercellular crosstalk between tumor and stromal cells during PMN establishment." (PMID 30792719, 2019). "S100A9 protein functions as an inflammatory mediator that contributes to inflammation and tumor progression." (PMID 31632476, 2019). "Elevated S100A9 expression in tumor stroma functions as an early recurrence marker in early-stage OSCC patients through increased tumor cell invasion, angiogenesis, macrophage recruitment and IL-6 production." (PMID 30871117, 2019). "S100A9, an important member of the calcium binding protein S100 family, is secreted mainly by inflammatory, tumor, and stromal cells." (PMID 31727865, 2019). "When the tumor suppressor gene SMAD4 is expressed by PDAC cells, S100A8 and S100A9 are produced by the tumor infiltrating inflammatory cells." (PMID 30764482, 2019). "The high correlation also indicated that S100A8 and S100A9 transcripts have potential to serve as surrogate markers for levels of stromal infiltration in tumor tissue." (PMID 30808902, 2019). "ROC curve analysis was performed to assess the ability of S100A9 to discriminate between tumor and normal bone tissues." (PMID 31055998, 2019). "Paired preoperative and postoperative serum samples from 21 patients were assessed by ELISA, and the result suggested that serum S100A9 was derived from the tumor tissue." (PMID 31632476, 2019). "When the signal is transmitted, the signaling transduction protein S100A9 is the target of the tumor-promoting signal, and it also activates downstream genes that promote tumor progression." (PMID 31126066, 2019). "S100A9 expression was significantly higher in tumor than in normal bone tissue samples (P = 0.0014)." (PMID 31055998, 2019).
tumor (continued). "It has been shown that S100A9 overexpression is correlated to invasion and metastasis in various cancers, and S100A9 directly enhances tumor cell malignancy by activating TLR4-mediated or RAGE-mediated signaling cascades." (PMID 31620141, 2019). "We also demonstrated that the expression level of S100a9 was significantly increased in the tumor site compared to the normal colon of CRC patients (normal = 51, CRC = 383)." (PMID 29991744, 2018). "The calprotectin complex consisting of S100A8 and S100A9 proteins has recently been identified as key driver of chronic and tumor promoting inflammation in skin carcinogenesis." (PMID 29563902, 2018). "We also assessed gene expression of various factors associated with the suppressive function of MDSCs including S100A8, S100A9, Nos3, Arg1 and Arg2 in BM-MDSCs compared to G-MDSCs from the tumor, spleen and lungs of tumor-bearing mice." (PMID 29677215, 2018). "While, several other studies have indicated that extracellular S100A8/S100A9 exhibits powerful anti-tumor responses by promoting cytotoxicity and apoptosis." (PMID 30558666, 2018). "S100A9+ MDSCs in PBMC were well correlated to tumor infiltrating CD68+ and S100A9+ cells, suggesting an origin of TAMs." (PMID 29484139, 2018). "Our IHC study also showed a plenty of S100A9-satined cells adhering to the inner surface and spreading in the vicinity of blood vessels in tumor tissues." (PMID 29484139, 2018). "S100A8 is highly expressed in the cytosol of some immune cells including neutrophils, macrophages, and dendritic cells, and is induced by toll-like receptor (TLR) agonists, and S100A9 inhibits myeloid differentiation thereby contributing to tumor growth." (PMID 29897930, 2018). "After normalisation, S100A9 was found to be up-regulated in all the tumor samples compared to its controls with p value < 0.05, which was consistent with the iTRAQ analysis." (PMID 29568375, 2018). "In turn, SAA stimulates its own transcription as well as that of the proinflammatory S100A8 and S100A9 proteins, strongly enhancing adhesion, migration and invasion of human and mouse tumour cells." (PMID 29788918, 2018). "S100A8 and S100A9 are induced by primary tumor and chemoattract CD11b+ bone marrow-derived cells in pre-metastatic lungs by us." (PMID 30167087, 2018). "This clinical relevance is partly due to S100A9+ MDSC-derived macrophages in the tumor microenvironment, which attenuate the cytotoxic effect of EGFR-TKIs on otherwise sensitive cancer cells." (PMID 29484139, 2018). "Neutralizing anti-S100A8 and anti-S100A9 antibodies blocked the morphological changes and migration of tumor cells and Mac 1-positive myeloid cells." (PMID 29416786, 2018). "Nonetheless, the tumor morphology and malignancy of anti-S100a9 treatment mice were consistent with the IgG-treated mice." (PMID 29326691, 2017). "Among tumor-derived individual signals, our study suggests potential key roles for S100A9 and CXCL12 among others." (PMID 28472073, 2017). "Increased S100a9 expression has been seen in tumor cells and tumor-infiltrating myeloid cells in many epithelial tumors." (PMID 29326691, 2017). "The expression of S100A9 in monocytes exerts a tumour-promoting effect upon co-culture with oral cancer cells, in particular by releasing IL-6 and the activation of NF-κB or STAT-3 that is not achieved in tumour cell monoculture." (PMID 28381274, 2017). "We performed SPECT imaging using an S100A9-specific antibody labeled with Indium-111 (In-111) in 4T1.2- and 67NR-tumor-bearing mice 19-21." (PMID 28744322, 2017). "Again, pro-inflammatory S100 proteins such as S100A8, S100A9 controls the trafficking and accumulation of MDSCs in tumor bearing host." (PMID 28414726, 2017). "The inflammatory response, tumor cell proliferation, and immune cells infiltration in the colon tissues were suppressed by anti-S100a9 antibody." (PMID 29326691, 2017).
tumor (continued). "The expression pattern of TREM1 was closely paralleled by the expression of IL1B and S100A9 which were also increased in the tumor tissue." (PMID 29093489, 2017). "The cell proliferation in tumor tissues of the CAC mice was decreased by anti-S100a9 Ab treatment comparing to IgG Ab treatment." (PMID 29326691, 2017). "Confocal microscopy of frozen lung sections from 4T1.2 tumor-bearing mice revealed increased intra- and extracellular S100A9 in areas of CCR2+CD115+ monocyte accumulation, thus confirming the in vivo imaging." (PMID 28744322, 2017). "S100A9, produced by tumor cells and by infiltrating myeloid suppressor cells, creates a tumor-promoting and immunosuppressive microenvironment in primary tumors and in pre-metastatic niches." (PMID 28472073, 2017). "The increased S100A9 signals in the spleen of 4T1.2 and 67NR tumor-bearing animals were accompanied by splenomegaly and changes in the cellular composition of the splenic cell populations." (PMID 28744322, 2017). "Increased S100A9-levels at day 10 after tumor implantation were indicative of the tumor-mediated immune remodeling and correlated with the consecutive tumor cell seeding into the lung." (PMID 28744322, 2017). "In TGCA, the data are insufficient to report HNSCC survival and patient tumor characteristics when only S100A8 or S100A9 was downregulated." (PMID 26883112, 2016). "OS cells treated with siRNA- S100A9 vectors groups or empty vectors groups were implanted in subcutaneous tissues of nude mice, and corresponding neoplasm volumes were measured every 7 days." (PMID 27020242, 2016). "The number of cells migrated across the polycarbonate membrane was also reduced after silence of S100A9, while the invasion of tumor cells was significantly inhibited." (PMID 27020242, 2016). "The up-regulation of S100A9 in tumor TIF was also found in these samples, especially with more than 15 folds upregulation in patient B3." (PMID 27216119, 2016). "The recent accumulative studies have demonstrated that the S100 family members, notably S100A9, played a critical role in tumor development and progression due to their involvement in survival, growth and metastasis of tumor cells." (PMID 27020242, 2016). "Reduction in MMP2 and MMP9 expression after S100A8 and S100A9 knockdown in the cancer cells suggests their regulation by the S100 proteins, and is consistent with decreased tumor cell migration and invasion." (PMID 27086923, 2016). "This study implicates S100A8 and S100A9 as important mediators of tumor cell aggressiveness, and highlights the therapeutic potential of S100A8 and S100A9 for interference of metastasis." (PMID 27086923, 2016). "Within the group of 17 proteins, four exhibited the most pronounced expression difference: IGFBP7, S100A9 and IL-10 were found strongly up-regulated in tumor, while MUC6 was markedly less abundant compared to the reference tissue." (PMID 27600085, 2016). "Collectively, these data suggest that monocytes/macrophages in liver metastases induced tumor cell proliferation, migration and invasion, and upregulated S100a8 and S100a9 expression through TNFα-induced ERK activation." (PMID 27086923, 2016). "Mice inoculated with S100A8-shRNA- or S100A9-shRNA-transfected MC38 or LLC cells had considerably reduced metastatic tumor burden compared with controls." (PMID 27086923, 2016). "It has been reported that both MCP1 and S100A9 mediate the migration and infiltration of CD11b+Gr1+ cells into inflammatory sites and tumor tissues and inhibit DC differentiation and function." (PMID 27478837, 2016). "In response to conditioned media from tumor-infiltrating monocytes/macrophages, cancer cells upregulated S100a8 and S100a9 messenger RNA expression through an extracellular signal-related kinase-dependent mechanism." (PMID 27086923, 2016). "S100A8 and S100A9 are known to influence tumor cell proliferation, survival, and migration as well as to stimulate migration and proliferation of neutrophils themselves." (PMID 28066438, 2016).
tumor (continued). "Culture of MC38 and LLC cancer cells in conditioned media from tumor-infiltrating monocytes/macrophages and granulocytes induced S100a8 and S100a9 mRNA expression." (PMID 27086923, 2016). "In this study, we surveyed the expression of S100A9 in human OS tissues and normal human bone tissues, 120 specimens from OS patients and 40 normal human bone tissues were evaluated by tumor tissue microarrays." (PMID 27020242, 2016). "Here we explored the significance of S100A8 and S100A9 induction by the myeloid cells in the tumor microenvironment." (PMID 27086923, 2016). "To determine the effects of S100A8 and S100A9 on tumor cell proliferation, migration and invasion, we downregulated both the genes in MC38 and LLC cells using lentiviral short hairpin RNA (shRNA)." (PMID 27086923, 2016). "Previous studies have shown that, over-expression of S100A9 in tumor stroma can inhibit the differentiation of dendritic cells and macrophages and induce accumulation of myeloid-derived suppressor cells, thus is partly responsible for immune defects in cancer." (PMID 27661117, 2016). "Down-regulation of S100A9 inhibited OS cellular proliferation, migration, invasion and cell cycle S phase in vitro and suppressed tumor formation in vivo with the reduction on PCNA and Ki67 proliferation index." (PMID 27020242, 2016). "Our data show that several S100 genes, i.e. S100A4, S100A6, S100A10, S100A8, and S100A9, are expressed at very high levels in both tumor cells and TAMs." (PMID 27215396, 2016). "More invasive extensions of the tumor colonies into the adjacent liver were evident in controls compared with the S100A8 or S100A9 knockdown cells." (PMID 27086923, 2016). "Our findings demonstrate that monocytes/macrophages in the metastatic liver microenvironment induce S100A8 and S100A9 in cancer cells, and that these proteins are essential for tumor cell migration and invasion." (PMID 27086923, 2016). "S100A8 and S100A9 also increase the motility of circulating cancer cells by p38 mitogen-activated protein kinase (MAPK)-mediated activation of tumor cell pseudopodia." (PMID 25673070, 2015). "We divided these patients into 2 groups, high and low, based on the mean S100A9 staining intensity in tumor or stroma." (PMID 26315114, 2015). "The release of S100A9 protein into extracellular milieu enhanced tumor cell invasion, transendothelial monocyte migration and angiogenic activity." (PMID 26315114, 2015). "The expression of S100A9 in one stromal component, monoctyes, also enhanced tumor cell aggressiveness." (PMID 26315114, 2015). "Together, S100A9 promoted TW-2.6 tumor formation as well as dominant increase of myeloid cell marker and IL-6 expression in vivo." (PMID 26315114, 2015). "Proteins S100A8 and S100A9 were upregulated in tumor tissues, which was consistent with that in the serum levels." (PMID 25673070, 2015). "The mRNA expression of IL-6, a multi-functional cytokine required for MDSC generation and tumor progression, was predominantly increased in S100A9-expressing human tumors and mouse stroma." (PMID 26315114, 2015). "S100A9-mediated release of IL-6 requires the crosstalk of tumor cells with monocytes through the activation of NF-κB and STAT-3." (PMID 26315114, 2015). "On the other hand, S100A9 is also known to affect migration of myeloid cells and MDSCs in particular into tumor tissue." (PMID 26673090, 2015). "S100A9 protein is chemotactic for monocytes and myeloid-derived suppressor cells (MDSCs), a heterogeneous population of immature myeloid cells with tumor-promoting function." (PMID 26315114, 2015). "In a murine model it has been shown that the inflammatory chemoattractants S100A8 and S100A9 released from primary B16 melanoma tumours pre-condition the lungs, create pre-metastatic niches and attract both tumour and inflammatory cells." (PMID 26082798, 2015).